SORT1 (sortilin 1)
Diseases named in the same sentence as SORT1 in open-access papers (continued):
Sharing a sentence is not in itself a finding about the gene and the disease.
endometrial cancer (2 papers, 2022 to 2024). Primary or metastatic malignant neoplasm involving the endometrium (mucous membrane that lines the endometrial cavity). "Therefore, the anticancer properties of the peptide-drug conjugate TH1902, a peptide that targets SORT1 and which is linked to docetaxel molecules, were investigated both in vitro using ovarian and endometrial cancer cell cultures and in vivo using xenograft models." (PMID 35454785, 2022). "SORT1 expression was next examined in a series of commercially available cell lines derived from human ovarian and endometrial cancers." (PMID 35454785, 2022). "In this study, the uptake of a fluorescently labeled peptide, used to generate TH1902, was first assessed to confirm the requirement of SORT1 for its internalization in SORT1-expressing ovarian and endometrial cancer cells." (PMID 35454785, 2022). "The expression of SORT1 has previously been shown to be strongly increased in human malignancies including ovarian and endometrial cancers." (PMID 35454785, 2022). "Overall, TH1902 shows better in vivo efficacy, compared to that of docetaxel and even paclitaxel, against SORT1-positive ovarian and endometrial cancers and could be safely combined with carboplatin." (PMID 35454785, 2022). "Likewise, in endometrial cancer, NT, NTR1, and SORT1 appear overexpressed, with NTR1 levels increasing with tumor grade, while their expression is lower or absent in normal tissues." (PMID 39519199, 2024).
frontotemporal dementia (2 papers, 2022 to 2024). Frontotemporal dementia (FTD) comprises a group of neurodegenerative disorders, characterized by progressive changes in behavior, executive dysfunction and language impairment, as a result of degeneration of the medial prefrontal and frontoinsular cortices. "This L-R binding was first identified in the brain, underscores SORT1’s role in mediating rapid endocytosis and lysosomal localization of GRN, central in the development of inherited frontotemporal lobar degeneration." (PMID 39143467, 2024).
glioma (2 papers, 2023 to 2025). A benign or malignant brain and spinal cord tumor that arises from glial cells (astrocytes, oligodendrocytes, ependymal cells). "A study on gliomas also showed SORT1 expression levels were significantly elevated in high-grade gliomas, and the expression levels were positively correlated with tumor malignancy." (PMID 40750784, 2025). "We first performed a data mining of sortilin gene (SORT1) expression using GEPIA2 and accessing the GBM and Low-Grade Glioma (LGG) datasets of The Cancer Genome Atlas (TCGA) database and GTEx." (PMID 37173980, 2023).
hyperlipidemia (2 papers, 2019 to 2020). "This study presented important evidence to support that E2F1 also serves as a promoter of hepatic secretion of VLDL and hyperlipidemia by modulating miR-378a-3p-SORT1 axis." (PMID 32226531, 2020). "Upon activation, this axis maintains activation of miR-378a-3p biogenesis, suppression of Sort1, increased stabilization and secretion of ApoB100, which subsequently facilitates hepatic secretion of VLDL and aggravates the pathogenesis of hyperlipidemia." (PMID 32226531, 2020). "Upon activation, this axis maintains activation of miR- 378a-3p biogenesis, suppression of Sort1, increased stabilization and secretion of ApoB100, which subsequently facilitates hepatic secretion of VLDL and aggravates the pathogenesis of hyperlipidemia and hypolipoproteinemia." (PMID 32226531, 2020).
melanoma (2 papers, 2020 to 2024). A malignant, usually aggressive tumor composed of atypical, neoplastic melanocytes. "High SORT1 expression was also shown in lysates from a murine B16-F10 melanoma cell line and from two human melanoma cell lines (A375 and SK-MEL-28), as well as from a positive control (human TNBC-derived MDA-MB-231)." (PMID 38482021, 2024). "To assess whether TH1902 could serve a SORT1 receptor-mediated chemotherapeutic approach in an immunocompetent syngeneic model, we first assessed SORT1 expression in murine B16-F10 melanoma cells along with other cell lines." (PMID 38482021, 2024). "These SORT1 expression levels in melanoma tissues are in accordance with previous evidence." (PMID 38482021, 2024). "SORT1-positive SK-MEL-28 and B16-F10 melanoma cells were selected for testing the anti-proliferative effect of docetaxel and TH1902." (PMID 38482021, 2024).
neuroblastoma (2 papers, 2013 to 2019). Neuroblastoma (NB) is the most common solid, extracranial childhood tumor. "Consistent with previous reports, downregulation of mTdp-43 in mouse N2a neuroblastoma cells by small inference RNA (siRNA) significantly increased the levels of the abnormal splicing variants: mSort1+Ex17b (sortilin 1 including exon 17b) and mTsn_ΔEx5 (translin with exon 5 deletion) (siTardbp)." (PMID 23922830, 2013). "Instead, in human M17 cells, TDP-43 LOF led to a significant 1.9-fold increase in total SORT1 protein levels, which was also confirmed in human neuroblastoma SK-N-BE cells." (PMID 31766750, 2019). "By analyzing SK-N-BE neuroblastoma cells as an alternative human neuronal cell model, we observed the same SORT1 gene expression pattern of M17 cells." (PMID 31766750, 2019).
schizophrenia (2 papers, 2016 to 2022). A major psychotic disorder characterized by abnormalities in the perception or expression of reality. "Human ARHGAP33 is associated with brain phenotypes and reduced SORT1 expression is found in patients with schizophrenia." (PMID 26839058, 2016). "Here the authors show that ARHGAP33 interacts with SORT1 to regulate TrkB trafficking, the dysfunction of which impairs synapse development and leads to schizophrenia-related behavioural abnormalities in mice." (PMID 26839058, 2016). "Furthermore, a correlated decrease in the ARHGAP33 and SORT1 expression levels was observed in the peripheral lymphocytes of schizophrenia patients." (PMID 26839058, 2016). "Interestingly, correlated decreases in ARHGAP33 and SORT1 expression levels are observed in the peripheral lymphocytes of schizophrenia patients." (PMID 26839058, 2016). "In this respect, ARHGAP33 and ARHGAP32 as well as SORT1 are unique in that they are regulators of intracellular protein trafficking, highlighting a novel role of the SNX-related proteins in the pathophysiology of schizophrenia." (PMID 26839058, 2016).
subarachnoid hemorrhage (2 papers, 2019 to 2025). A serious neurological disorder characterized by intracranial hemorrhage into the subarachnoid space. "Sortilin-1, known to rise significantly following brain injuries such as subarachnoid hemorrhage and Visinin-like protein 1, a neuronal calcium-sensor protein and established marker of neuronal injury, were also significantly upregulated." (PMID 40663395, 2025). "Previous study showed that PGRN could reduce neuronal apoptosis after subarachnoid hemorrhage by activation of Sortilin 1 signaling pathways." (PMID 31775776, 2019).
triple-negative breast carcinoma (2 papers, 2023 to 2024). An invasive breast carcinoma which is negative for expression of estrogen receptor (ER), progesterone receptor (PR), and human epidermal growth factor receptor 2 (HER2). "Theratechnologies developed a SORT1-targeted peptide–drug conjugate (PDC)_TH1902 for the treatment of SORT1-positive triple-negative breast cancer." (PMID 38139459, 2023). "In recent preclinical studies performed in immunocompromised animal models, which are unable to produce mature T-cells, TH1902 was effective against several human SORT1-positive xenograft models including triple-negative breast cancer (TNBC), ovarian cancer, and endometrial cancer." (PMID 38482021, 2024).
tuberculosis (2 papers, 2016 to 2023). A chronic, recurrent infection caused by the bacterium Mycobacterium tuberculosis. "To address the role of sortilin in susceptibility to tuberculosis in vivo, we infected Sort1−/− and Sort1+/+ mice with M. tuberculosis H37Rv." (PMID 27389464, 2016).
abdominal aortic aneurysm (1 paper, 2023). Enlargement and ballooning of the vessel that supplies arterial blood to the abdomen, pelvis and legs. "The present study shows that the single nucleotide polymorphisms (SNPs) of the genes CDKN2BAS rs10757278, LPA rs3798220, SORT1 rs599839, DAB2IP rs7025486, and IL6R rs2228145 are associated with the development of abdominal aortic aneurysms (AAA) in a study population." (PMID 37893562, 2023).
aneurysm (1 paper, 2023). Bulging or ballooning in an area of an artery secondary to arterial wall weakening.
Anxiety (1 paper, 2018). Intense feelings of nervousness, tension, or panic often arise in response to interpersonal stresses. "Finally, we tested the ability of WT and Sort1−/− mice to bury glass marbles, a test able to detect anxiety and obsessive compulsive disorders related phenotypes." (PMID 30127743, 2018). "However and paradoxically, Sort1−/− mice displayed an anxiety-like behavior in several anxiety-related tests including the light dark and the marbles burying tests." (PMID 30127743, 2018). "The serum concentration of corticosterone in basal conditions remained unchanged between WT and Sort1−/− mice (p = 0.642) indicating that the anxiety-like behavior of Sort1−/− mice was not the consequence of the hormone increase." (PMID 30127743, 2018).
aortic valve calcification (1 paper, 2024). "A recent study has reported the role of MAPK and YAP pathways in SORT1-induced aortic valve calcification following mechanical injury." (PMID 38255751, 2024).
Arthritis (1 paper, 2020). Inflammation of a joint. "Up-regulation of PGRN by anti-SORT1 mAb may also be applicable to inflammatory diseases such as arthritis." (PMID 33384578, 2020). "This suggests that SORT1 down-regulation is a key mechanism in increasing PGRN levels by anti-SORT1 antibodies and is a promising target for PGRN boosting therapy in disorders such as FTD-PGRN or arthritis, as indicated by Pgrn KO mice phenotype." (PMID 33384578, 2020).
Atherosclerotic lesion (1 paper, 2021). A lesion associated with atherosclerosis, a multifactorial and multipart progressive disease manifested by the focal development within the arterial wall of lesions, that ranges from the development of a fatty streak, plaque progression, and plaque disruption.
breast tumor (1 paper, 2023). "We hypothesize that the high turnover of SORT1 enables SORT1-targeted ADC to be a powerful agent for the treatment of SORT1-positive breast tumor." (PMID 38139459, 2023).
Cirrhosis (1 paper, 2024). A chronic disorder of the liver in which liver tissue becomes scarred and is partially replaced by regenerative nodules and fibrotic tissue resulting in loss of liver function. "Multi-stage analysis revealed the lowest SORT1 expression in normal liver tissues, which gradually increased as the liver disease progressed from viral hepatitis to hepatic fibrosis, cirrhosis, and HCC." (PMID 39209807, 2024).
coronary atherosclerosis (1 paper, 2025). Atherosclerosis of the coronary vasculature. "Gene markers associated with coronary atherosclerosis, such as JCAD, GUCY1A3, PCSK9, and SORT1, have demonstrated significant diagnostic and prognostic value in multiple studies." (PMID 39858645, 2025).
endothelial dysfunction (1 paper, 2013). In vascular diseases, endothelial dysfunction is a systemic pathological state of the endothelium (the inner lining of blood vessels) and can be broadly defined as an imbalance between vasodilating and vasoconstricting substances produced by (or acting on) the endothelium. "In this regard, we previously showed that the rs599839 polymorphism located in the lp13.3 genomic region (SORT1) was associated with endothelial dysfunction in RA." (PMID 24286297, 2013).
epithelial ovarian tumors (1 paper, 2022). "Overall, SORT1 expression was higher in about 77% of all epithelial ovarian tumors tested, the percentage increased to 94% outside of LGSC." (PMID 35454785, 2022).
gallstones (1 paper, 2023). Solid crystalline precipitates in the biliary tract, usually formed in the gallbladder, resulting in the condition of cholelithiasis. "SORT1 knockout mice fed a high-cholesterol diet showed decreased free cholesterol accumulation in the liver, increased bile acid synthesis, decreased cholesterol secretion in bile, and no gallstone formation." (PMID 37958806, 2023).
gynecological cancers (1 paper, 2024). "Clinical studies and models have demonstrated that TH1902, by leveraging SORT1-mediated endocytosis, notably suppresses tumor growth more effectively than conventional chemotherapy agents like docetaxel alone, suggesting its potential as a targeted therapy for SORT1-positive gynecological cancers." (PMID 39033780, 2024).
Intellectual disability (1 paper, 2021). "Given the relevance of sortilin 1 functions in the nervous system and considering the presence of seizures and intellectual disability in some patients with RS, another hypothesis to consider is a possible effect on sortilin 1 phosphorylation in FAM20C deficiency." (PMID 34360805, 2021).
leukemia (1 paper, 2025). A malignant (clonal) hematologic disorder, involving hematopoietic stem cells and characterized by the presence of primitive or atypical myeloid or lymphoid cells in the bone marrow and the blood. "The present work found an NT receptor overexpression in pediatric leukemia samples, in which p75NTR was overexpressed in B-ALL as well as SORT1 in T-ALL disease." (PMID 40427122, 2025).
liver disease (1 paper, 2024). "To validate SORT1 overexpression in malignant cells at the single-cell level, we conducted an additional analysis using GepLiver DB, an integrative liver expression atlas covering developmental and liver disease phases." (PMID 39209807, 2024).
lysosomal storage disorders (1 paper, 2020). "These proteins use SORT1 to be properly delivered to lysosome and their deficiency causes lysosomal storage disorders." (PMID 33384578, 2020).
multiple myeloma (1 paper, 2025). "A previous study demonstrated that SORT1/LAMP2-mediated extracellular vesicle secretion and cell adhesion resulted in lenalidomide resistance in multiple myeloma." (PMID 40750784, 2025).
neuropathic pain (1 paper, 2020). Chronic pain caused by damage to nerve fibers. "Removal of cell surface SORT1 by anti-SORT1 mAb may block BDNF signaling and anti-SORT1 mAb may be beneficial for the treatment of neuropathic pain, a major clinical challenge resulting from peripheral nerve trauma or disease." (PMID 33384578, 2020).
ovarian tumors (1 paper, 2022). "A marked increase was observed in SORT1 levels between healthy tissue and either malignant primary ovarian tumors or metastases from ovarian tumors." (PMID 35454785, 2022). "SORT1 is located within cells where it is involved in the trafficking of vesicles between intracellular compartments, and its siRNA-mediated gene silencing in an ovarian tumor cell line leads to increased apoptosis and diminished proliferation." (PMID 35454785, 2022).
pancreatic ductal adenocarcinoma (1 paper, 2025). An infiltrating adenocarcinoma that arises from the epithelial cells of the pancreas. "A previous study showed migration features of human pancreatic ductal adenocarcinoma cell are mainly mediated through the SORT1/NTR3 receptor with modified adhesion abilities and activation of small Rho GTPases." (PMID 40750784, 2025).
pituitary cancer (1 paper, 2024). A primary or metastatic malignant neoplasm affecting the pituitary gland. "SORT1 expression is elevated in several human malignancies including breast, ovarian, prostate, colon, pancreatic, skin, and pituitary cancers." (PMID 38482021, 2024).
preeclampsia (1 paper, 2023). Preeclampsia is a hypertensive disorder of pregnancy that is characterized by new-onset hypertension with proteinuria presenting after 20 weeks of gestation, and depending on mild or severe forms may initially present with severe headache, visual disturbances, and hyperreflexia. "In the extravillous cytotrophoblasts, SORT1 is decreased in severe preeclampsia compared to normal pregnancy." (PMID 36698175, 2023).
prion disease (1 paper, 2017). A transmissible disease that is caused by a protein that is able to induce abnormal folding of normal cellular proteins, leading to characteristic spongiform brain changes, which are associated with neuronal loss without an inflammatory response. "We then evaluated the effects of sortilin deficiency on the pathogenesis of prion disease using sortilin-KO (Sort1-/-) mice." (PMID 28665987, 2017).
sitosterolemia (1 paper, 2014). A rare autosomal recessive sterol storage disease characterized by the accumulation of phytosterols in the blood and tissues. "Genetic variation in ABCG5 and ABCG8 has been associated with sitosterolemia while GWAS has recently implicated SORT1 as a novel locus for LDL cholesterol." (PMID 24503134, 2014).
tauopathies (1 paper, 2025). "Immunostaining revealed diverse SORT1 distribution in tauopathies, ranging from predominantly neuronal to mixed neuronal and astrocytic localization." (PMID 40545554, 2025).
Tremor (1 paper, 2015). An unintentional, oscillating to-and-fro muscle movement about a joint axis. "Interestingly, all of our SORT1 mutation carriers were shown later to carry elevated levels of LDL cholesterol, suggesting a possible role of cholesterol homeostasis in the pathogenesis of tremor." (PMID 26297037, 2015).